PAK1 (p21 (RAC1) activated kinase 1)
Diseases named in the same sentence as PAK1 in open-access papers (continued):
Sharing a sentence is not in itself a finding about the gene and the disease.
cancer (continued). "Of the 82 unique prognostic biomarkers identified, meta-analyses showed several promising biomarkers, including COX-2, PAK-1, p14ARF, PD-L1, MET, LC3B and LGR5, associated to each hallmark of cancer feature." (PMID 30185893, 2018). "PAK1 is responsible for a variety of human diseases/disorders and it is currently considered to be a major therapeutic target for the treatment of cancer, diabetes, hypertension, and neurodegenerative disorders." (PMID 30262742, 2018). "Given the current lack of clinical Pak small molecule inhibitors, most prior studies of Pak function in cancer have relied on siRNA-mediated or shRNA-mediated gene knockdown or on Pak1 gene knockout in cells and/or animals." (PMID 30150766, 2018). "Okinawa propolis (OP) and its major ingredients were reported to have anti-cancer effects and lifespan-extending effects on Caenorhabditis elegans through inactivation of the oncogenic kinase, p21-activated kinase 1 (PAK1)." (PMID 30262742, 2018). "Pak1 in particular is suspected of playing a driver role in several different cancers, and animals bearing deletions in Pak1 have been used to study its roles in malignancy." (PMID 30150766, 2018). "Contrary, yet little is known about the potential drugability of PAK-1 in cancer, even though the recently elucidated central role in oncogenic signaling has enhanced interest in small-molecule based PAK-1 targeting." (PMID 30185893, 2018). "Some studies have observed that the PAK1/Akt axis plays the important roles in proliferation in cancer or regulates the process of arrhythmias." (PMID 29422044, 2018). "Of the 82 unique prognostic biomarkers identified, meta-analyses showed prominent biomarkers, including COX-2, PAK-1, p14ARF, PD-L1, MET, LC3B, IGFBP7 and LGR5, associated to each hallmark of cancer." (PMID 30185893, 2018). "Although PAK1 is well known for its role in cancer development, our data has highlighted for the first time a role for PAK1 in the immune response to tumours." (PMID 28629331, 2017). "But the contribution of PAK1 to cancer autophagy, prognosis, therapeutic target and PAK1 signaling pathway remains limited." (PMID 28186966, 2017). "On the basis of PAK1-PUMA binding, we have revealed that single novel compound can suppress PAK1 activity and induce cell death only in PAK1 activated and Bcl-2 overexpressed cancer cells." (PMID 28423593, 2017). "PAKs are involved in the innate immune response, and accumulating evidence implicates PAK1 in colon inflammation and cancer." (PMID 28423670, 2017). "Considering various role of PAK1 in cancer progression and initiation, PAK1 is very attractive target protein for development of anti-cancer drug." (PMID 28423593, 2017). "Since AKT signaling is essential for cancer growth, PAK1 inhibition would also suppress the AKT activity." (PMID 28423593, 2017). "Considering our result, IPP-14 and its derivatives would be possible candidates for PAK1 and p21 induction targeted anti-cancer drug." (PMID 28423593, 2017). "For a long time, inhibition of PAK1 has been suggested as one of plausible strategy for anti-cancer treatment." (PMID 28423593, 2017). "The threonine/serine kinase P21-activated kinase 1 (PAK1) has been reported to stimulate the growth and/or metastasis of many cancers including those in brain, breast, lung, ovarian, prostate, stomach, colon/rectum, liver and pancreas." (PMID 28629331, 2017). "PAK1 and Rac1 reportedly play important roles within cancer cell signaling networks and contribute to invasive and metastatic phenotypes." (PMID 27027431, 2016). "Although it has been suggested that PAK1 influences the prognosis of various cancer types, current knowledge of the contribution of PAK1 to cancer prognosis remains limited." (PMID 27027431, 2016). "Previous studies have described that overactivation or overexpression of PAK1 is strongly correlated with cancers." (PMID 27121078, 2016).
cancer (continued). "Although the roles of PAK1 have been widely studied in a variety of cancers and cancer cells, other roles of PAK1 still remain to be elucidated." (PMID 27121078, 2016). "We had ventured into an under-investigated area in cancer biology i.e., the role of PAK1 in the progression of OSCC." (PMID 27229476, 2016). "Accordingly, the activity of PAK1 is up-regulated through protein overexpression or gene amplification in cancer tissues." (PMID 27121078, 2016). "Up-regulation of Pak1 and Pak4 has also been observed in other human cancers, such as breast and colon cancers." (PMID 26218748, 2015). "The PAK1 is a serine/threonine protein kinase which is stimulated by active Rac1 and Cdc42-GTPases, and has been found to be key regulator of cancer-cell signaling networks." (PMID 25888627, 2015). "Of note, PAK1 is upregulated in cancers of gastrointestinal tracts including colorectal, gastric cancer and gastroesophageal junction adenocarcinoma." (PMID 26023713, 2015). "P21-activated kinase 1 (PAK1) is expressed at high levels in many human cancer tissues and is closely related to mitosis of tumor cells, regeneration of the cytoskeleton structure, cell migration and apoptosis." (PMID 26516313, 2015). "Up-regulation of Pak1 and Pak4 mRNA and protein expression was also found in cancer cell lines (HEC-1B, HEC-1A and RL95-2) compared with normal endometrial cells by qPCR and Western blot analysis, respectively." (PMID 26218748, 2015). "The PAK1 gene is located on 11q13-q14 and this region is frequently amplified in many human cancers, with a complex structure harboring multiple potential oncogenic drivers 22,24." (PMID 26377044, 2015). "Hyperactivation of PAK1 has been reported in numerous cancers, thus making PAK1 appealing as pharmacological target for gene therapy." (PMID 25093037, 2014). "In this review, we will highlight the expression and signaling pathways of PAKs in human cancers, in particular its functional role in hepatocarcinogenesis, furthermore, the potential therapeutic application of PAK1 inhibitor will be discussed." (PMID 25093037, 2014). "PAK1 or PAK2 expression is upregulated in some types of cancer and PAKs were suggested to be a suitable target for anti-cancer therapy as well as for the treatment of airway hyperresponsiveness or in conditions of vascular leak." (PMID 24664099, 2014). "Subsequent investigations showed that the expression and activity of PAK1 was upregulated in several other human cancers." (PMID 25182632, 2014). "The actin cytoskeleton dynamics mechanism in tumor biology behavior, as the regulation of the actin cytoskeleton in cancer prevention and control in the sense Rac1, Pak1 and Rock1 is worth studying." (PMID 23298303, 2014). "PAK1 activation also stimulates anti-apoptotic pathways, such as the Pak-Raf1-Bad and NFκB pathways, rendering PAK1 attractive as a cancer therapeutic target." (PMID 23936510, 2013). "Careful examination of sections revealed that stronger PAK1 expression was in the samples with more severe cancer-cell infiltration away from main tumor mass breaking into surrounding tissues, as compared with those with less severe cancer-cell infiltration." (PMID 24236193, 2013). "Both in stomach and esophagus, PAK1 transcripts were higher in cancer tissue than in normal tissue (both P<0.05)." (PMID 24236193, 2013). "The crucial roles of PAK1 in tumorigenesis and metastasis derive from both in vitro and in vivo models and provide the rationale for developing PAK1 inhibitors as anti-cancer agents." (PMID 24236193, 2013). "Encouraging evidence that many tumors respond to PAK1 inhibitors expands opportunities for the development of novel anti-cancer drugs." (PMID 24236193, 2013). "The activated PAK1 in turn promotes cancer cell invasion and metastasis by phosphorylating key regulators involved in cytoskeleton reorganization, such as Lim kinase (LIMK) and the P41-ARC subunit of the ARP2/3." (PMID 23936510, 2013).
cancer (continued). "PAK1 is frequently overexpressed and hyperactivated by dysregulation of a number of signaling pathways in human cancer cells that are stimulated by growth factor receptors such as EGFR, PDGFR, and VEGFR." (PMID 23936510, 2013). "Once activated, PAK1 phosphorylates its downstream substrates, that are responsible for various biological effects of PAK1 kinase in cancer cells." (PMID 23950862, 2013). "These two examples (PAK1 and RhoGDI2) illustrate the importance of Rho GTPases in determining the metastatic potential of cancer cells." (PMID 22623902, 2012). "The role of group I PAKs is more clearly demonstrated in cancer progression as PAK1 overexpression is seen is several tumor types." (PMID 22848689, 2012). "It has been reported that Pak1, the best characterized member of this family, shows increased expression and activity in human cancers." (PMID 20426825, 2010). "Emerging evidence has suggested that PAK1 is required for the progression and metastasis of cancer cells by mediating growth factor-induced motility and invasiveness." (PMID 21209852, 2010). "Rac1 and Pak1 have recently been shown to be key regulators of cancer cell signaling networks, and there are several lines of evidence linking Rac1 and Pak1 to the acquisition of migratory, invasive, and metastatic phenotypes." (PMID 20426825, 2010). "As well as our findings in patients with UC-UUT, overexpression of Rac1 and Pak1 has been reported in several other human cancers." (PMID 20426825, 2010). "Targeting the PAK1/mTOR/p70 S6K pathway could lead to novel treatments that inhibit cancer growth and metastasis, ultimately improving patient outcomes." (PMID 41459112, 2026). "Our findings establish that regulation of RAS stability by T148 phosphorylation is preferentially active across diverse hematologic malignancies, including MM, AML, and GCB DLBCL, and point to PAK1/2 inhibition as a key therapeutic vulnerability in these cancers." (PMID 41542462, 2026). "Thus, cancer cells acquire even more metastatic properties through a signaling network regulated by PAK1." (PMID 40864802, 2025). "It has been shown that cancer cell focal adhesions are regulated by PAK1 promoting PDAC metastasis." (PMID 40274768, 2025). "It is known that PAK1 is overexpressed in almost all types of cancer." (PMID 40864802, 2025). "Furthermore, PAK1 mediates multiple additional pathways that affect growth, survival and therapeutic resistance in cancer cells." (PMID 41154654, 2025). "Super-EBS treatment inhibited Rac-1, Cdc42 and p-PAK1 expression levels in both cancer cell lines." (PMID 39781466, 2025). "However, this therapeutic approach must be carried out with knowledge of evidence that increased Pak1 activity plays a role in adverse aging mechanisms, neurodegenerative disorders, and oncogenesis and metastasis in various cancers." (PMID 40065530, 2025). "Previous studies have reported a role of PAK1 in endothelial cell growth and migration, which could contribute to a pathological angiogenesis in cancer." (PMID 40943273, 2025). "Importantly, in multiple model systems, the Ras-driven pathway of oncogenic transformation was shown to depend on the function of RAC1 and its immediate downstream effector PAK1, representing a potentially exploitable vulnerability in a subset of cancers." (PMID 41154654, 2025). "Inhibition of PAK1, the primary downstream target of Rac1 responsible for vimentin Ser38 phosphorylation greatly reduced metastasis, highlighting a promising potential for developing drugs targeting this function for cancer treatment." (PMID 38915055, 2024). "Furthermore, the use of an inhibitor of p21-activated kinase PAK1, one of the kinases responsible for vimentin Ser38 phosphorylation, significantly reduced cancer metastasis in animal models." (PMID 38915055, 2024).
cancer (continued). "Generally, group I PAKs (PAK1-3) are in a self-inhibiting state under physiological conditions and are activated by binding to CDC42, and cancer development could be promoted by the CDC42-PAK1 axis." (PMID 36812247, 2023). "Overactivation of Rac1/PAK1 signaling is a common feature of multiple types of cancer." (PMID 36951547, 2023). "PAK1 functions as a node in the activation of multiple signalling pathways in many cancers." (PMID 37537668, 2023). "Many papers have reported that PAK1 induces migration in cancer cells by regulating MAPK and NF-κB." (PMID 38188678, 2023). "PAK1, with pivotal roles in brain development and in cancer, also regulates MAPK." (PMID 37124926, 2023). "On the other hand, there is some functional overlap between PAKs, which brings up the possibility that a treated cancer may evolve a resistance to complete PAK1 inhibition by elevating the activity of other isoforms." (PMID 37830586, 2023). "Indeed, there is abundant evidence of PAK1 being essential for the survival and proliferation of at least some cancer types, and this dependence correlates with the nature of oncogenic drivers in these malignancies." (PMID 37830586, 2023). "We examined whether PAK1 signaling participates in the induction of cancer cell migration and invasion by IL-1β." (PMID 38188678, 2023). "Elevated PAK1 has been correlated to cancer cell infiltration and metastasis in colorectal cancer." (PMID 37190165, 2023). "This suggests that PAK1 suppression may improve tumor resistance by the stroma in addition to disabling the cancer cell proliferation, vascular invasion, and metastasis." (PMID 37190165, 2023). "PAK1 expression correlated to cancer cell infiltration and metastasis in patients." (PMID 37190165, 2023). "Notably, the CDC42/PAK1 complex offers a wealth of structural,mutagenesis, and binding affinity data because of its central rolein cellular signaling and cancer progression." (PMID 35679463, 2022). "Accordingly, PAK1 may promote the occurrence and development of GBM via the abnormal activation of PAK1, which suggests that the development of specific PAK1 inhibitors to reduce p-PAK1 for the treatment of some cancers may be very promising." (PMID 36064705, 2022). "Interestingly, the JAK2-induced tyrosine phosphorylation of PAK1 appears to be involved in most cancers." (PMID 36230657, 2022). "PAK1 was also involved in the activation, proliferation, and apoptosis of pancreatic stellate cells, and further, the in interaction of stellate cells with cancer cells." (PMID 36230657, 2022). "Notably, our test case—the CDC42/PAK1 complex—ishighly relevant for cancer drug discovery, being involved in cancercell invasion and metastasis." (PMID 35679463, 2022). "The ability of cancer cells to migrate to other cells and invade other tissues requires actin cytoskeleton reorganization, which is controlled by the duo of ras-related C3 botulinum toxin substrate 1 (Rac1) and p21 protein-activated kinase 1 (PAK1)." (PMID 34164422, 2021). "Toxicity of 15K is therefore more specific towards cancer cells through inhibiting PAK1." (PMID 34471161, 2021). "Based on the selective anticancer effects of 15K against PAK1-dependent cancer cells, we hypothesize that it may act as an allosteric PAK1 inhibitor." (PMID 34471161, 2021). "However, additional substrates that mediate the oncogenic effects of Pak1 in different types of cancer remain to be identified." (PMID 35111748, 2021). "In addition, it has been shown that one member of the Pak family, Pak1, is amplified and/or overexpressed in different types of cancer, including 25–30% of breast tumor samples and cancer cell lines." (PMID 35111748, 2021). "In the PAK family proteins, PAK1 has been shown to promote cancer cell migration." (PMID 34381046, 2021). "Previous study showed that PAK1 can activate IL‐6 expression via JaK2 activation in cancer stem cell, whether JaK2 involved in the PAK1‐mediated IL‐6 production needs further study to confirm." (PMID 33124146, 2020).
cancer (continued). "Overall, PAK1 has become a hallmarker and therapeutic target for a variety of cancers." (PMID 32863957, 2020). "Targeting PAK1 with small molecules holds promise as a viable therapeutic strategy for cancers." (PMID 32863957, 2020). "Finally, in the process of extravasation of cancer cells to the secondary area and to new tissues and organs, chronic inflammation induced by PAK1 promotes cancer cell survival in the new environment through the remodeling of the extracellular matrix." (PMID 32863957, 2020). "Several studies have tested the therapeutic effect of PAK-1 inhibitors on cancer cell growth." (PMID 33321758, 2020). "Therefore, it is no coincidence that these cannabinoids (CBD and THC) would act directly or indirectly via a PAK1-mediated pathway to exert their anti-cancer function." (PMID 33126623, 2020). "Together, these results demonstrated that 7j is a novel potent PAK1 inhibitor, which may provide a candidate drug for future cancer therapy." (PMID 32752894, 2020). "By exploring the complex regulatory molecular mechanism of PAK1 in cancer progression and the current situation of small molecule drug development, it might be helpful to develop better PAK1 anticancer drugs and novel PAK1-related cancer treatment strategies." (PMID 32863957, 2020). "The cooperative inhibition of PAK1 and Wnt/β-Catenin is a new strategy for cancer therapy." (PMID 32863957, 2020). "Even though studies have suggested that IPA-3 may be a viable therapeutic option for cancers with altered PAK-1 expression, IPA-3 has limitations due to its poor stability and efficacy in vivo." (PMID 33321758, 2020). "Indeed, PAK1 has gained interest as a promising target for cancer therapy as it was found to be frequently overexpressed in different types of cancer tissues and its abundance correlates with poor prognosis." (PMID 33066011, 2020). "As a crucial family of serine/threonine kinases, PAK1 affects plenty of cellular processes and served an important role in different biological functions in diverse diseases, including cell immigration, invasion, growth and apoptosis in various cancers." (PMID 33124146, 2020). "The downstream effector PAK1 belongs to the Rho family of small GTPases that include Cdc42 and Rac1, which are essential regulators of cellular migration and invasion and promote cancer metastasis." (PMID 33261184, 2020). "Similar PAK1‐dependent motility was also observed in other p27‐mislocalized cancer cell lines." (PMID 31872963, 2020). "Moreover, PAK1 plays a major role in diseases, such as nervous system disorders including Alzheimer and cancer development including malignant progression." (PMID 32047750, 2020). "Although cancer cells may face a bleak situation during metastasis, when they survive in new tissues, PAK1 can promote their adaptation to the new environment, rendering them dormant or enabling them to further breed." (PMID 32863957, 2020). "In fact, PAK1 and Wnt/β-Catenin do contribute to cancer development." (PMID 32863957, 2020). "One of the most studied biological functions of PAK1 is their contribution in cancer metastasis." (PMID 32863957, 2020). "Studies of the relationship between PAK1 and cancer were started in the mid-1990s." (PMID 32863957, 2020). "Furthermore, we provide our perspective on current advances and future challenges of PAK1 in cancer." (PMID 32863957, 2020). "PAK1 also contributes to cancer progression through inducing JNK activation." (PMID 32863957, 2020). "PAK1 also performs roles in the regulation of apoptosis and NF-κB pathway for cancer development." (PMID 32863957, 2020). "We also discovered p21‐activated kinase 1 (PAK1) as a novel downstream effector of cytoplasmic p27‐mediated cell motility that may represent a therapeutic target in OS and other cancers that harbor p27 mislocalization." (PMID 31872963, 2020). "Many PAK1 inhibitors have been developed as potential preclinical agents for cancer therapy." (PMID 32863957, 2020).